TNFRSF12A (TNF receptor superfamily member 12A)
Diseases named in the same sentence as TNFRSF12A in open-access papers (continued):
Sharing a sentence is not in itself a finding about the gene and the disease.
cholestasis (continued). "Next, we investigated whether the accumulated BAs in cholestasis induce TNFRSF12A expression and pyroptosis of hepatocytes." (PMID 36690641, 2023). "Targeting TNFRSF12A or blocking its mediated hepatocyte pyroptosis might be a new therapeutic strategy for treating cholestasis." (PMID 36690641, 2023). "Currently, the regulatory mechanisms controlling hepatic TNFRSF12A expression in human cholestasis remain unknown." (PMID 36690641, 2023). "Therefore, we examined whether FXR is involved in regulatinghepatic TNFRSF12A expression in cholestasis." (PMID 36690641, 2023). "As such, targeting TNFRSF12A could be a promising approach to treating cholestasis." (PMID 36690641, 2023). "However, regulatory mechanisms controlling the hepatocyte Tnfrsf12a gene expression and its functional significance in human cholestasis remain unclear." (PMID 36690641, 2023). "Therefore, targeting TNFRSF12A could be a new approach for treating cholestasis." (PMID 36690641, 2023). "Initially, the accumulated intrahepatic BAs during cholestasis activate the JNK signaling pathway to stimulate TNFRSF12A expression at the transcriptional level through increasing the binding activity of c-JUN to the TNFRSF12A promoter." (PMID 36690641, 2023).
chronic hepatitis C (3 papers, 2016 to 2025). "TNFRSF12A (Tumor necrosis factor receptor superfamily member 12 A) is also nearly undetectable in normal adult livers but substantially increased in hepatic progenitor cells during chronic liver diseases, including MASH, alcoholic liver disease, and chronic hepatitis C." (PMID 39746606, 2025). "Interestingly, TNFRSF12A is nearly undetectable in normal adult livers but substantially increased in hepatic progenitor cells during chronic liver diseases, including NASH, alcoholic liver disease, and chronic hepatitis C." (PMID 36690641, 2023).
pulmonary fibrosis (3 papers, 2024 to 2025). Chronic progressive interstitial lung disorder characterized by the replacement of the lung tissue by connective tissue, leading to progressive dyspnea, respiratory failure, or right heart failure. "Compared to lung fibroblasts from normal control samples, fibroblast samples obtained from pulmonary fibrosis showed an upregulation of TNFRSF12A." (PMID 39075394, 2024). "The results above suggest that the fibroblast receptor factor TNFRSF12A might play a crucial role in the development of pulmonary fibrosis." (PMID 39075394, 2024).
squamous cell carcinoma (3 papers, 2012 to 2022). A carcinoma arising from squamous epithelial cells. "Interestingly, several genes found to be differentially enriched in the BC-2 subpopulation, such as Tppp3, Tnfrsf12a, and Cav1 have been associated with severity or aggressiveness of squamous carcinoma in various organs." (PMID 36178196, 2022).
colon adenocarcinoma (2 papers, 2025). "SERPINE1 is negatively associated with immune cells in colon adenocarcinoma, while TNFRSF12A (FN14a) drives tumour growth and metastasis." (PMID 40340807, 2025).
colorectal tumors (2 papers, 2013 to 2022). "In particular the gene TNFRSF12A (also known as TWEAK receptor) seems to be critical as it was also detected as overexpressed in GBM and colorectal tumors samples." (PMID 24195083, 2013).
essential hypertension (2 papers, 2018 to 2025). Hypertension that presents without an identifiable cause. "Calca is associated with Parkinson diseases and essential hypertension, while Tnfrsf12a is an important molecule in cardiac hypertrophy disease, cardiac shock retinal inflammation, and atherosclerosis-related diseases." (PMID 29681850, 2018).
influenza (2 papers, 2015 to 2023). An acute viral infection of the respiratory tract, occurring in isolated cases, in epidemics, or in pandemics; it is caused by serologically different strains of viruses (influenzaviruses) designated A, B, and C, has a 3-day incubation period, and usually lasts for 3 to 10 days. "Several other pro-apoptotic genes including TNFRSF12A, DDIT3, and CDKN1A were upregulated in SUS animals, indicating that they may also contribute to apoptotic events during influenza infection in swine." (PMID 26393920, 2015).
leukemia (2 papers, 2025). A malignant (clonal) hematologic disorder, involving hematopoietic stem cells and characterized by the presence of primitive or atypical myeloid or lymphoid cells in the bone marrow and the blood. "Unexpectedly, the nearby naïve CD4 T cells and DCs had significantly higher expression of TNFRSF12A, which codes for the corresponding receptor TWEAKR (also known as FN14 and CD266) than that of the same cell types at least 30 μm away from the closest leukemia cell." (PMID 40632867, 2025). "Surprisingly, the nearby naïve CD4 T cells and DCs had significantly higher expression of TNFRSF12A, which codes for the corresponding receptor TWEAKR (also known as FN14, CD266) than that of the same cell types at least 30 microns away from the closest leukemia cell." (PMID 39975227, 2025).
lung disease (2 papers, 2022 to 2024). "The TNFRSF12A signaling pathway has been identified in IPF to accelerate collagen synthesis through the regulation of matrix metalloproteinase 9 (MMP9), which has been suggested as a therapeutic target in several lung diseases." (PMID 39767799, 2024).
oral cancer (2 papers, 2022). "All above findings indicated the different roles of TNFRSF25 and TNFRSF12A in p-EMT tumor cells in non- vs. metastasis conditions of oral cancer, and TNFRSF12A is highly associated with tumor cell metastasis transcription factor SNAI2." (PMID 35742914, 2022). "The top 3 IRGPs most strongly and positively correlated with the outcome of oral cancer were TNFRSF12A|TNC, PLAU|DEFB1, and TAP|IGHG2." (PMID 35804390, 2022).
schizophrenia (2 papers, 2021 to 2026). A major psychotic disorder characterized by abnormalities in the perception or expression of reality. "The role of TWEAKR (TNFRSF12A) has not been widely explored in psychiatric disorders, and to our knowledge, this is the first study to find significantly increased DR4 (TNFRSF10A) mRNA in high-inflammation schizophrenia and bipolar postmortem brains." (PMID 41567988, 2026).
triple-negative breast carcinoma (2 papers, 2024 to 2025). An invasive breast carcinoma which is negative for expression of estrogen receptor (ER), progesterone receptor (PR), and human epidermal growth factor receptor 2 (HER2). "This study systematically elucidated the pro-tumor mechanism and therapeutic value of TNFRSF12A in triple-negative breast cancer (TNBC) by integrating multi-omics analysis with experimental validation." (PMID 41300305, 2025).
alcohol (1 paper, 2025). "In humans, ALDH2 hypomethylation has been reported in livers from alcohol-associated cirrhosis, while tumor necrosis factor receptor superfamily member 12A (TNFRSF12A) hypomethylation in alcohol-related HCC correlates with increased expression and poor prognosis." (PMID 41462685, 2025).
alcohol abuse (1 paper, 2019). The use of alcoholic beverages to excess, either on individual occasions ("binge drinking") or as a regular practice. "However, in 116 HCC cases which have the alcohol abuse risk factor, there was a significant prognostic association of TNFRSF12A high expression, hypomethylated cg00510447 and hypomethylated cg26808293." (PMID 31998364, 2019). "However, mechanisms underlying the hypomethylation of TNFRSF12A in HCC with alcohol abuse history remain unclear." (PMID 31998364, 2019). "The study to investigate the mechanisms by which alcohol abuse mediated changes in the methylation level of TNFRSF12A affect the occurrence, development and prognosis of HCC were under warranted." (PMID 31998364, 2019). "Expression of DNMT1, DNMT3B and DNMT3L was identified to be negatively correlated with the expression of TNFRSF12A in 116 HCC with alcohol abuse (r <−0.22, p < 0.01)." (PMID 31998364, 2019). "Firstly, we found a higher expression of TNFRSF12A have worse prognosis in HCC patients with a history of alcohol abuse." (PMID 31998364, 2019). "Expression of TNFRSF12A was higher in HCC cases with a history of alcohol abuse (p = 0.003)." (PMID 31998364, 2019). "Thus, in this study we mined two publicly available datasets to detect the association between DNA methylation level of CpG sites in gene TNFRSF12A and the development of HCC in those with alcohol abuse history." (PMID 31998364, 2019). "The further mechanism analysis revealed that the DNA methyltransferases DNMT3L might regulate TNFRSF12A methylation and affect the occurrence, development and prognosis of HCC, especially in patients with a history of alcohol abuse." (PMID 31998364, 2019).
alcoholic cirrhosis (1 paper, 2019). "Our results showed that the methylation status of cg00510447 and cg26808293 corresponding to TNFRSF12A was negatively correlated to the prognosis of HCC with alcoholic cirrhosis." (PMID 31998364, 2019).
alcoholic hepatitis (1 paper, 2019). Acute hepatitis resulting from ingestion of alcohol. "Colocalization of TNFRSF12A with progenitor-derived neonatal hepatocytes in the liver from alcoholic hepatitis patients suggests a potential role for this receptor in progenitor cell differentiation." (PMID 31998364, 2019). "TNFRSF12A is mainly expressed in a subset of hepatocytes and progenitor cells of patients with alcoholic hepatitis." (PMID 31998364, 2019). "In the GSE28619 dataset, out of five DNA methylases, only DNMT3Lwas identified to be negatively correlated with TNFRSF12A expression (r = −0.66, p < 0.001) in 15 cases of alcoholic hepatitis." (PMID 31998364, 2019). "Further analysis revealed both the cg00510447 and cg26808293 sites in the TNFRSF12A gene were significantly hypomethylated in HCC patients than normal tissues, similarly, these were observed in cases of alcoholic hepatitis." (PMID 31998364, 2019). "Tumor necrosis factor (TNF) receptor superfamily member 12A (TNFRSF12A; also known as CD266, and TWEAKR) was reported to be upregulated in alcoholic hepatitis." (PMID 31998364, 2019).
Allergy (1 paper, 2022). An allergy is an immune response or reaction to substances that are usually not harmful. "Several top-ranking genetic perturbagens including PAK1, GSR, RBM15 and TNFRSF12A have been indicated by previous studies to be involved in allergy/asthma." (PMID 35606385, 2022).
astrocytic tumor (1 paper, 2022). A glial tumor of the brain or spinal cord showing astrocytic differentiation. "Moreover, TNFRSF12A is a strong prognostic predictor for patients diagnosed with oligodendroglial or astrocytic tumors." (PMID 35646656, 2022).
Bell's palsy (1 paper, 2025). Partial or complete paralysis of the facial muscles of one side of a person's face. "In this study, 70 inflammation-related proteins that may be causally associated with Bell’s palsy were identified by MR analysis, and 7 significantly related proteins were screened by external dataset validation, including BLVRB, HMOX2, TNFRSF12A, DEFB128, ITM2A, DDX58 and VEGF-A." (PMID 40299566, 2025).
Cholestatic liver disease (1 paper, 2025). "The member 12A of the tumor necrosis factor receptor family (TNFRSF12A) plays a critical role in cholestatic liver disease." (PMID 40932836, 2025).
epilepsy (1 paper, 2021). A brain disorder characterized by episodes of abnormally increased neuronal discharge resulting in transient episodes of sensory or motor neurological dysfunction, or psychic dysfunction. "A previous study shows that differential expression of TNFRSF12A and DNA methylation contributes to the development of brain diseases such as epilepsy." (PMID 33643183, 2021).
head and neck squamous cell carcinoma (1 paper, 2024). A squamous cell carcinoma that arises from any of the following anatomic sites: lip and oral cavity, nasal cavity, paranasal sinuses, pharynx, larynx, and salivary glands. "To substantiate the prognostic significance of our model, we recruited a clinical cohort consisting of 20 patients with head and neck squamous cell carcinoma at various clinical stages to verify the expression of the four genes (CCND1, FTH1, YWHAG and TNFRSF12A)." (PMID 37882107, 2024).
Hepatic steatosis (1 paper, 2024). Steatosis is a term used to denote lipid accumulation within hepatocytes. "In control diet fed mice, Nrf2 deficiency was nonconsequential, while Nrf1 and combined deficiency exacerbated the effect, as demonstrated by hepatic steatosis as well as significant or trending increases in hepatic triglyceride and expression of Ccl2, Ccnb1, Col1a1, Col3a1, Ihh, and Tnfrsf12a." (PMID 39125617, 2024).
intestinal-type gastric adenocarcinoma (1 paper, 2025). "TNFRSF12A+ CAF plays a key role in the immunosuppression of intestinal-type gastric adenocarcinoma (IGAC) (a type of STAD) acts as a key mediator in immunosuppression and has potential as an immunomodulator." (PMID 40391219, 2025).
liposarcoma (1 paper, 2017). A usually painless malignant tumor that arises from adipose tissue. "Other genes of angiogenesis that show upregulation in DAKO liposarcoma are Tnc, Ptn and Tnfrsf12a." (PMID 28459858, 2017).
oral squamous cell carcinoma (1 paper, 2024). "Previous studies demonstrated the role of TNFRSF12A in oral squamous cell carcinoma." (PMID 38660262, 2024).
serous carcinoma (1 paper, 2024). "Those tumors with HRD were all diagnosed as high grade serous carcinoma, specifically harboring fusions involving NRG1 and the JAG1, SPON1, and TNFRSF12A partner genes." (PMID 39575425, 2024).
stomach adenocarcinoma (1 paper, 2025). "TNFRSF12A is abnormally expressed in various malignancies, especially in stomach adenocarcinoma (STAD), which is related to tumor invasiveness and prognosis of patients." (PMID 40391219, 2025).
viral encephalitis (1 paper, 2025). Encephalitis resulting from viral infection. "Beyond viral encephalitis, we found induction of the pathway in EAE, whereas for other brain diseases only limited parallel upregulation of microglial Tnfsf12 and oligodendrocyte Tnfrsf12a was observed." (PMID 40450318, 2025).
tumor (122 papers, 2011 to 2026). "Gene set enrichment analysis implicated this gene in tumor-associated neovascularization regulation, with experimental validation demonstrating markedly impaired vascular formation capacity following TNFRSF12A knockdown." (PMID 41300305, 2025). "Tumor oriented Fn14 signaling in experimental mouse models resulted in a clinical phenotype similar to CCS in which the administration of anti-TNFRSF12A antibodies inhibited weight loss." (PMID 35743911, 2022). "Anti-TNFRSF12A antibodies can inhibit tumor growth moderately and significantly prolong life expectancy by alleviating tumor-induced weight loss." (PMID 33937046, 2021). "It has been suggested that TNFRSF12A expression is abnormally upregulated in numerous carcinomas, such as colorectal cancer, glioma, and breast cancer, which is closely associated with tumor aggressiveness and patient prognosis." (PMID 40391219, 2025). "In vitro cytotoxicity assays revealed that genetic ablation of TNFRSF12A augmented T-cell-mediated tumor cell lysis." (PMID 41300305, 2025). "TWEAK originated from T cells and mast cells, implicating it in tumor aggressiveness, and cancer cells clearly expressed TNFRSF12A." (PMID 41228323, 2025). "In summary, this study systematically elucidates how TNFRSF12A propels TNBC malignant progression by remodeling the tumor immune microenvironment and promoting angiogenesis." (PMID 41300305, 2025). "We detected that TNFRSF12A, IL1R1, ELN and CYP26B1 were unfavorable prognostic factors that were overexpressed in tumor tissues and associated with poor survival in the TCGA-BLCA cohort." (PMID 38216619, 2024). "Knocking down TNFRSF12A in these cell lines resulted in a notable reduction in the viability of tumor cells, as seen by the CCK-8 test." (PMID 39224598, 2024). "Remarkably, after TNFRSF12A knockdown, significant inhibition of tumor cell migration was observed (p < 0.05)." (PMID 38292868, 2024). "TNFRSF12A appears to be an important protein in the proliferation, invasion, and migration of tumour cells and is overexpressed in many different cancers." (PMID 36835246, 2023). "A discrete association with the findings in the present study can be noticed; TNFRSF12A showed lower expression in HPV-positive tumours, in line with our results from the serum analysis." (PMID 36835246, 2023). "Concurrently, DM-aKG treatment was sufficient to inhibit Tnfrsf12a transcription in the primary tumor." (PMID 37761958, 2023). "It is reported that TNFRSF12A/TNFRSF12 (only known ligand for TNFRSF12A) signaling is related to tumor metastasis and progression, as well as immune surveillance and angiogenesis." (PMID 35646656, 2022). "The analysis discovered four subtypes of CAFs: one p-EMT tumor cell population, and cycling tumor cells as well as TNFSF12-TNFRSF25/TNFRSF12A interactions between CAFs and p-EMT tumor cells during tumor metastasis." (PMID 35742914, 2022). "To investigate the significance of our risk model, we then compared the expression levels of 9 factors in CMS and found TNFRSF12A demonstrated the most significant difference between tumor and normal tissues." (PMID 34434928, 2021). "The protein-level verification based on the HPA database showed that the upregulation and downregulation of proteins between normal and tumor samples were consistent with the expression of TNFRSF12A." (PMID 33643183, 2021). "It has been proved that TNFRSF12A, which plays a role in tumor growth and metastasis, is highly expressed in solid tumor types." (PMID 33643183, 2021). "In order to study the specific effect of macrophages on tumor cells through the common L–R pairs (TNFSF12–TNFRSF12A and SPP1–CD44), we further calculated the correlation between the TNFRSF12A or CD44 expression and hallmark signature scores in cancer cells." (PMID 34676217, 2021).